MTOR (mechanistic target of rapamycin kinase)
Diseases named in the same sentence as MTOR in open-access papers (continued):
Sharing a sentence is not in itself a finding about the gene and the disease.
colorectal cancer (continued). "Given that the PI3K/AKT/mTOR pathway is important to metabolic, growth, and proliferative processes of the cell, genetic variation and abnormal expression or activity of its components has drawn the attention of those studying cancer biology, colorectal cancer included." (PMID 27203393, 2017). "Here we review phosphatidylinositol-3-kinase (PI3K)/Akt/mTOR signaling as one of the primary mechanisms for sustaining tumor outgrowth and metastasis, recent advances in the development of mTOR inhibitors, and current studies addressing mTOR activation/inhibition in colorectal cancer (CRC)." (PMID 24393708, 2014). "Colorectal cancer often involves dysregulation of the mTOR pathway, leading to activation of the AKT/mTOR axis and increased expression of c-Myc and HIF-1α; the former promotes glycolysis, and the latter accelerates the metabolic rate in colon cancer cells." (PMID 41584038, 2026). "Hsa_circRNA_002144 promotes colorectal cancer growth and metastasis through the miR-615-5p/LARP1/mTOR pathway." (PMID 40018039, 2025). "PLOD2 has been reported as an oncogenic gene in colorectal cancer and functions by stabilizing USP15, leading to AKT/mTOR-regulated progrowth signaling." (PMID 40757636, 2025). "This study demonstrates that 8-Nitrotryp inhibits colorectal cancer progression through dual suppression of the TGF-β/SMAD and PI3K/AKT/mTOR pathways." (PMID 40918508, 2025). "Consistent with this regulatory relationship, a study in colorectal cancer indicated that macrophage-derived SHP-2 can inhibit TEK protein phosphorylation, thereby inactivating the PI3K/AKT/mTOR pathway and suppressing metastasis." (PMID 40808675, 2025). "For colorectal cancer, everolimus inhibits the PI3K/AKT/mTOR axis to disrupt cellular transformation and tumor progression while reducing drug resistance, highlighting its therapeutic potential in this malignancy." (PMID 40771929, 2025). "As a dual inhibitor of PI3K and mTOR, NVP-BEZ235 has shown to induce autophagy in multiple myeloma cells, colorectal cancer cells, and esophageal cancer cells." (PMID 40771929, 2025). "For colorectal cancer, gentisic acid was reported to inhibit metastasis via blocking GPR81-mediated degradation of DEPDC5, thereby inhibiting mTOR-driven EMT signaling." (PMID 41515404, 2025). "Another study reported that QI galls water extract induced apoptosis and autophagic cell death in colorectal cancer cells through the accumulation of intracellular reactive oxygen species (ROS) and modulation of the AKT/mTOR signaling pathway." (PMID 40933552, 2025). "In colorectal cancer cells, for example, BPA induces the overexpression of GOLPH3, which promotes malignant behavior by activating the PI3K/AKT/mTOR cascade and ROS-driven HIF-1α/VEGF signaling, even under hypoxic conditions." (PMID 41440754, 2025). "Previous studies have shown that in colorectal cancer research, Delicaflavone can induce the accumulation of ROS, suppress the PI3K/AKT/mTOR and Ras/MEK/Erk signaling cascades, inhibit the proliferation of colorectal cancer cells, and promote apoptosis." (PMID 40643461, 2025). "One example of another possible confounding factor is the E3 ligase FBX8 which has been shown to target mTOR for ubiquitin-mediated degradation, a process shown to be essential for FBX8-induced cell proliferation and invasion in colorectal cancer (CRC)." (PMID 40872852, 2025). "This study identified Faecalibaculum rodentium as a novel probiotic that suppresses colorectal cancer (CRC) via acetate, which enhances CD8+ T-cell immunity by blocking PDPN-CLEC-2 and induces tumor cell apoptosis through PI3K/AKT/mTOR pathway." (PMID 40693815, 2025). "In colorectal cancer (CRC) models, the combination of the mTOR inhibitor temsirolimus and the autophagy inhibitor chloroquine significantly enhanced the antitumor effects of radiotherapy, as evidenced by a marked increase in apoptosis rates." (PMID 40725100, 2025).
colorectal cancer (continued). "In colorectal cancer, ECM components such as collagen 1 have been shown to activate PI3K/AKT/mTOR signalling and promote stemness and metastasis." (PMID 40860666, 2025). "Zotarolimus, a semi-synthetic inhibitor of the mammalian target of rapamycin (mTOR), demonstrated marked anti-tumor effects in HCT-116 colorectal cancer xenograft models." (PMID 41149466, 2025). "It has been shown that SAL dose-dependently reduces colorectal cancer cell viability and promotes apoptosis and autophagy through the inhibition of the PI3K/Akt/mTOR pathway." (PMID 39097833, 2024). "In colorectal cancer, the AKT/mTOR pathway acts as a negative regulator of autophagy, and IATL reduces associated protein levels to induce cell death and autophagy." (PMID 39382942, 2024). "Inhibition of MDH2 reduces NADH levels and cellular ATP production in colorectal cancer cells, which in turn inactivates ACC and mTOR signaling pathways." (PMID 39403185, 2024). "Mutations in other components of the pathway, including PTEN, TSC1, PPP2R1A, and MTOR, were also significantly more frequent in CDX2-suppressed colorectal cancers." (PMID 39452477, 2024). "For example, in colorectal cancer, the addition of JQ1 to mTOR inhibitors was thought to synergize through suppressing oncogenic kinases, while in rhabdomyosarcoma, combined BETi + mTORC1/2i–induced necroptosis-mediated cell death." (PMID 38060314, 2024). "For instance, Astragalus membranaceus saponins have exhibited anticancer activity by modulating the PI3K/Akt/mTOR and ERK signaling pathways in colorectal cancer cells HCT116 and HT-29." (PMID 38952445, 2024). "Additionally, MSC-Exos was enriched in miR-100, which could modulate the miR-100/mTOR/miR-143 axis, while mTOR and miR-143 could diminish the cell proliferation and enhance cell apoptosis in colorectal cancer (CRC) by affecting glycolysis, cell cycle progression, and other mechanisms." (PMID 39161894, 2024). "The mTOR STN plays a vital role in the regulation of cell survival, metabolism, growth, and protein synthesis, it has emerged as an effective target for colorectal cancer therapy." (PMID 38051091, 2024). "On the other hand, CARMN directly interacted with miR‐5683 and they had a synergistic effect on colorectal cancer growth suppression, through degrading FGF2 mRNA to inhibit Akt/mTOR pathway and induce apoptosis/autophagy." (PMID 39039912, 2024). "In fact, some malignancies, such as non-small-cell lung, breast, prostate, and colorectal cancer, exhibit an abnormal activation of PI3K/AKT/mTOR signaling." (PMID 39469631, 2024). "mTOR signaling pathway suppresses the expression of GAS5 and establishes a feedback mechanism with miR-34a in colorectal cancer cells to mediate CRC cell macroautophagy." (PMID 39830506, 2024). "Kinase inhibitors combined with mTOR inhibitors, DNA damage-inducing drugs or HDAC inhibitors showed benefit, particularly for ovarian, melanoma, prostate, lung and colorectal carcinomas." (PMID 38287066, 2024). "Graphene oxide can also induce autophagic death of HCT116 cells by activating the ROS-dependent AMPK/mTOR/ULK1 pathway, thereby exerting obvious anti-colorectal cancer effects both in vivo and in vitro." (PMID 38239356, 2023). "Studies have demonstrated the efficacy of Palbociclib (CDK 4/6 inhibitor), Gedatolisib (PI3K/mTOR dual inhibitor) and PD0325901 (MEK1/2 inhibitor) in colorectal cancer (CRC), however single agent therapeutics are often limited by the development of resistance." (PMID 37326340, 2023). "During glutaminolysis inhibition in colorectal cancer, activating transcription factor 4 (ATF4) is increased to reduce mTOR signaling by transcriptionally activating the mTOR suppressor DNA damage-inducible transcript 4 (DDIT4)." (PMID 36900220, 2023). "Similar results were found in colorectal cancer where FBXW7 decreased tumor burden of colorectal carcinoma by negative regulation of enolase-1 (ENO1), NK2, mTOR, and PTEN." (PMID 37752997, 2023).
colorectal cancer (continued). "Meanwhile, in colorectal cancer, FAT4 has been found to regulate PI3K activity in the PI3K/AKT/mTOR signaling pathway, inhibit tumor growth, and contribute to preventing EMT25." (PMID 37735184, 2023). "TAMs promote oxaliplatin resistance in colorectal cancer; M2-polarized TAMs are responsible for cancer resistance to cisplatin, and chemokines secreted by TAMs activate the PI3K/Akt/mTOR signalling pathway, thereby promoting resistance." (PMID 36693064, 2023). "A small pilot study shows that Simvastatin administration recapitulates the downregulation of phosphorylated mTOR and induces a tentative increase in BMP in colorectal cancer patients." (PMID 37887409, 2023). "In colorectal cancer, OGT and O-GlcNAc activate the Akt/mTOR signaling pathway to control tumor progression." (PMID 37838167, 2023). "Studies on colorectal cancer also support our finding, invasion and metastasis of colorectal cancer cells promoted by CTSK that stimulates the release of cytokines such as IL10 and IL17 through activation of the mTOR pathway." (PMID 37198626, 2023). "In this study, we aimed to investigate the expression level of HRK in colorectal cancer and to demonstrate that the effect of HRK on the biological function of colorectal cancer cells is regulated through the PI3K/AKT/mTOR pathway." (PMID 36568155, 2022). "It has been reported that Rictor/mTOR is involved in regulating EMT, motility, and metastasis of colorectal cancer via RhoA and Rac1 signaling pathways." (PMID 35982899, 2022). "In examining a series of shikonin derivatives for their inhibitory effects on colorectal cancer progression, DSK was found to induce cell apoptosis through the attenuation of PI3K-Akt-mTOR signaling pathways." (PMID 35806120, 2022). "Tim-4 promotes the growth of colorectal cancer by activating angiogenesis and recruiting TAMs via the PI3K/AKT/mTOR signaling pathway." (PMID 36059952, 2022). "We have recently provided evidence for upregulation of PDGF expression in UICC stage I–IV primary colorectal cancer (CRC) and demonstrated PDGF-mediated induction of PI3K/Akt/mTOR signaling in CRC cell lines." (PMID 36264073, 2022). "From the figure, it is apparent that the JAK/STAT3, the PI3K/AKT/mTOR, and the RAS/RAF/ERK pathways are highly up-regulated and are possibly the main reason for an out of control cell proliferation in colorectal cancer." (PMID 33596259, 2021). "A similar downregulation of mTOR and Akt was observed upon exposure to metals in PC12 cells and colorectal cancer cells (HCT116 and Caco-2 cells), indicating cellular stress." (PMID 33671655, 2021). "In colorectal cancer and cholangiocarcinoma, TRIM59 was shown to promote proliferation, but this was thought to be through the PI3K/AKT or PI3K/AKT/mTOR signaling pathway, respectively." (PMID 34065345, 2021). "miR-27a that upregulate in colorectal cancer is closely related to glycolysis mediating chemotherapy resistance through hampering AMPK and enhancing mammalian target of rapamycin (mTOR) signaling." (PMID 34786210, 2021). "Various signaling pathways regulate cellular proliferation, differentiation, and immortalization of colorectal cancer, especially Wnt/β-catenin, PI3K/AKT/mTOR and TGF-beta/Smad signaling." (PMID 34764977, 2021). "With cisplatin-resistant colorectal cancer cells in vitro and in vivo, APG induces autophagic cell death, overcomes cisplatin resistance, and blocks xenograft tumor growth by inhibiting the mTOR pathway." (PMID 34948250, 2021). "The mammalian target of rapamycin (mTOR), as a key site for PI3K to link 4E-BP1 and S6K1, plays an important role in the treatment of colorectal cancer." (PMID 32000660, 2020). "In conclusion, we functionally assessed the PI3K/AKT/mTOR pathway in a permanent CTC line, namely CTC-MCC-41, derived from a patient with colorectal cancer." (PMID 32962206, 2020).
colorectal cancer (continued). "In this regard, luteolin was already reported to alter antioxidant activity, modulate the MAPK and p-IGF-1R/PI3K/AKT/mTOR signaling pathways, and induce mitochondrial dysfunction in GBM, colorectal cancers and other malignancies." (PMID 33291443, 2020). "In colorectal cancer, FBX8, another tumor-suppressing E3 ligase, exerts a metastasis suppressor function by degrading mTOR." (PMID 32131492, 2020). "The expression level of lncRNA SLCO4A–AS1 was upregulated in colorectal cancer tissues, and positively correlated with that of partition-defective 3 (PARD3), a downstream effector of mTOR and AMPK in the initiation of autophagy." (PMID 33050642, 2020). "On the other hand, the effect of verbascoside on mTOR has also been tested showing the ability of this compound to inactivate PI3K/Akt and activate the PI3K/Akt/mTOR signaling pathway in PC12 cells and colorectal cancer cells." (PMID 32013273, 2020). "In another study, aspirin inhibited mTOR signaling, activated AMPK, and induced autophagy in colorectal cancer cells." (PMID 31624493, 2019). "Compound K induces autophagy-mediated apoptosis through AMPK/mTOR and JNK pathways in human NSCLC A549 and H1975 cells, while it also induces autophagy and apoptosis through ROS and JNK pathways in human colorectal cancer HCT-116 cells." (PMID 31719837, 2019). "Together, using the colorectal cancer cell line SW480 and Drosophila as model systems, we show that the mTOR pathway regulates CTPS cytoophidium assembly." (PMID 30857853, 2019). "Circ-FBXW7 controls the progression of CRC through NEK2, mTOR, and PTEN signaling pathways and its overexpression inhibits colorectal cancer cell migration and invasion, suggesting the potential therapeutic target for CRC treatment." (PMID 31519156, 2019). "The pathway enrichment analysis demonstrated that the nodes were significantly correlated with pathways in cancer, FoxO, miRNAs in cancer, colorectal cancer, VEGF, proteoglycans in cancer, HIF‐1, PI3K‐Akt, mTOR, and central carbon metabolism in cancer." (PMID 31448575, 2019). "We have previously shown that compound-7g inhibits colorectal cancer cell proliferation and survival by inducing cell cycle arrest and PI3K/AKT/mTOR pathway blockage." (PMID 31357480, 2019). "The underlying mechanism of compound-7g mediated anti-tumor activity in colorectal cancer cells was that it provokes G2/M cell cycle arrest, mitochondria-related apoptosis and inhibition of PI3K/AKT/mTOR pathway." (PMID 31357480, 2019). "To determine CI values in our panel of 47 human colorectal cancer cell lines we first established GI50 values for cobimetinib, pictilisib or the dual mTOR–pan-class I PI3K inhibitor apitolisib." (PMID 30905967, 2019). "We clearly demonstrated the anticancer molecular mechanisms of A. cinnamomea in colorectal cancer, revealing that A. cinnamomea induces autophagic cell death via the CHOP/TRB3/Akt/mTOR pathway." (PMID 30479369, 2018). "Previous study has proved that aspirin inhibits mTOR, activates AMPK, and induces autophagy in colorectal cancer cells." (PMID 29088823, 2017). "The combination of mTOR inhibitor and ERK inhibitor promotes apoptosis and tumor regression in mouse models of colorectal cancers." (PMID 28423618, 2017). "Elevated mTOR activity regulates EMT, motility, and metastasis of colorectal cancer via RhoA and Rac1 signaling pathways." (PMID 28831205, 2017).
colorectal cancer (continued). "Recently, in a phase I clinical trial a partial response was seen in a colorectal cancer patient treated with LY3023414, a dual PI3K/mTOR inhibitor." (PMID 26863299, 2016). "As to the association between CRC and diabetes, meformin has also been found to be a potential drug against colorectal cancer through the regulation of AMPK and mammalian target of rapamycin (mTOR)—signaling pathway." (PMID 26939025, 2016). "Most importantly, the EGFR signalling cascade involving PI3K/AKT/mTOR and Raf/MEK/ERK pathways are particularly relevant, since they are commonly activated in several cancer entities, including colorectal cancer." (PMID 27095166, 2016). "We initially examined the effect of BRAF/MEK and PI3K/MTOR pathway inhibitors on cell signaling and autophagy of BRAFV600E bearing colorectal cancer cell lines, in order to have a first indication on the potential regulation of autophagy by these two pathways." (PMID 26802026, 2016). "In conclusion, our present data show, for the first time, that Sal B is a novel autophagy inducer and exerts its antitumor activity as a single agent in colorectal cancer cells, both in vitro and in vivo, through the suppression of AKT/mTOR pathway." (PMID 27557491, 2016). "Using a panel of BRAF V600E and WT colorectal cancer cell lines and in vitro selected resistant culture, and xenograft models, we demonstrate here that BRAFV600E confers resistance to mTOR inhibitors." (PMID 27351224, 2016). "We observed a co-upregulation of the insulin-like growth factor receptor (IGF-1R)/AKT/mammalian target of rapamycin (mTOR) [InAT] axis and the mevalonate-isoprenoid biosynthesis (MIB) pathways in colorectal cancer stem cells (CSCs) in an unbiased approach." (PMID 25895029, 2015). "When colorectal cancer cells were treated with aspirin, there was a significant increase in AMPK activation and inhibition of downstream mTOR signaling." (PMID 25812084, 2015). "Recent evidences have emphasized the interplay between mTOR signaling and P-gp/MDR1-mediated MDR in hepatocellular carcinomas and colorectal cancer." (PMID 26098947, 2015). "It has also been described previously that treatment with rapamycin, an inhibitor of mTOR, resulted in decreased MDR1 transcription activity in colorectal cancer and eukaryotic cells." (PMID 26098947, 2015). "In the current study we describe the enhanced anti-tumor activity of the dual PI3K/mTOR inhibitor PF-502 and the MEK inhibitor PD-901 in in vitro and in vivo models of colorectal cancer." (PMID 25401499, 2014). "We explored the ability of representative phosphatidylinositol-3-kinase (PI3 Kinase)/mTOR and HSP90 inhibitors to overcome TRAIL resistance by increasing apoptosis in colorectal cancer models." (PMID 23852390, 2013). "In colorectal cancer cells, APN promotes cell survival during glucose deprivation by AMPKα and PPARα activation and IGF-1/PI3k/Akt/mTOR pathway inhibition." (PMID 23894332, 2013). "We have shown here that PI-103 and 17-AAG, as representative potent and selective PI3 Kinase/mTOR and HSP90 inhibitors, respectively, were able to increase sensitivity to TRAIL in colorectal cancer cells." (PMID 23852390, 2013). "This study evaluated the MEK inhibitors AZD6244 and PD0325901, alone and in combination with the dual mTOR/PI3K inhibitor NVP-BEZ235 or the PI3K inhibitor GDC-0941, in three colorectal cancer cell lines." (PMID 22415236, 2012). "Therefore, targeting mTOR in colorectal cancer might be a successful strategy." (PMID 20226010, 2010).